FAM222A (family with sequence similarity 222 member A)
Synonyms: C12orf34; FLJ14721
Tractability: No criterion of Open Targets' tractability assessment is met for any kind of drug.
Gene: Protein-coding gene on chromosome 12 (109,713,825 to 109,770,495, forward strand). Ensembl gene ENSG00000139438.
Subcellular location (Human Protein Atlas): Golgi apparatus; Cell Junctions; Midbody ring
Genetic constraint (gnomAD): Loss-of-function variants: 7 observed, 17.53 expected, observed/expected ratio (o/e) 0.4, 90% interval 0.23 to 0.75. The upper end of that interval is the gene's LOEUF score, 0.75, which puts it in group 3 of 6, group 1 being the genes least tolerant of losing a copy. Missense variants: 573 observed, 568.54 expected, observed/expected ratio (o/e) 1.01, 90% interval 0.94 to 1.08. Synonymous variants: 294 observed, 265.74 expected, observed/expected ratio (o/e) 1.11, 90% interval 1 to 1.22.
Homologues: Orthologues: chimpanzee FAM222A (99% identical), macaque FAM222A (98% identical), pig FAM222A (93% identical), dog FAM222A (92% identical), rabbit FAM222A (92% identical), mouse Fam222a (91% identical), guinea pig FAM222A (90% identical), rat Fam222a (85% identical), tropical clawed frog fam222a (61% identical), zebrafish fam222aa (61% identical), zebrafish fam222ab (27% identical). Paralogues in human: FAM222B (32% identical).
Diseases named in the same sentence as FAM222A in open-access papers:
FAM222A is named in the same sentence as 10 diseases in open-access papers, as found by Europe PMC text mining. Sharing a sentence is not in itself a finding about the gene and the disease. The quoted sentences say what the papers report.
Brain atrophy (3 papers, 2020 to 2024). Partial or complete wasting (loss) of brain tissue that was once present. "Recent studies have reported that FAM222A as a putative brain atrophy susceptibility gene and that the protein encoded by FAM222A is pathologically relevant in Alzheimer disease and Nasu–Hakola disease." (PMID 33923623, 2021). "In conclusion, we have reported FAM222A as a likely gene associated with AD-related regional brain atrophy, which encodes an amyloid plaque core protein pathologically involved in Aβ assembly and amyloid deposition." (PMID 31964863, 2020). "FAM222A, a gene putatively involved in brain atrophy susceptibility but also closely associated with AD, was one of the glial RECE-loop genes; its expression during brain development was reduced between embryo and birth but was significantly induced after birth." (PMID 38175672, 2024). "Here, we report FAM222A as a putative brain atrophy susceptibility gene." (PMID 31964863, 2020). "The large independent AD brain imaging dataset including GWAS studies is not available at this time, making it difficult to further validate the genetic link between FAM222A and AD-related brain atrophy." (PMID 31964863, 2020). "Our cross-phenotype association analysis of imaging genetics indicates a potential link between FAM222A and AD-related regional brain atrophy." (PMID 31964863, 2020). "In this study the authors identify a possible link between the gene FAM222A and brain atrophy." (PMID 31964863, 2020).
Atrophy (1 paper, 2020). Any weakening or degeneration, especially through lack of use. "In people diagnosed with AD or mild cognitive impairment (MCI), a proportion of whom can progress to AD, FAM222A is associated with the module enriched for atrophy in AD-affected brain regions." (PMID 31964863, 2020).
cervical cancer (1 paper, 2021). A primary or metastatic malignant neoplasm involving the cervix. "Based on Kaplan‐Meier analysis, PCBP1-AS1 and four mRNAs (FAM222A, FHAD1, WDR62, and SBK1) were identified as potential prognostic factors for cervical cancer patients." (PMID 33833992, 2021).
dementia (1 paper, 2020). Loss of intellectual abilities interfering with an individual's social and occupational functions. "Our findings therefore not only inform future genetic studies of FAM222A, but also encourage detailed pathophysiological investigation of its encoded Aggregatin for AD and related dementia." (PMID 31964863, 2020).
gastric cancer (1 paper, 2021). A primary or metastatic malignant neoplasm involving the stomach. "It was reported that FAM222a is related to chemotherapy resistance in gastric cancer, and its antisense RNA can regulate the migration of non-small cell lung cancer cells." (PMID 33833992, 2021).
Obesity (1 paper, 2015). Accumulation of substantial excess body fat. "Further evaluation of the obesity-related loci from VIVA LA FAMILIA in IRASFS revealed nominal association for rs2823615 (PDOM = 7.86x10-3 with SAT), an intronic SNP in the Family with Sequence Similarity 222 Member A gene (FAM222A)." (PMID 26599207, 2015).
tumor (1 paper, 2021). "The results showed that the expression of PCBP1-AS1, FAM222A, FHAD1, WDR62, and SBK1 was significantly correlated with tumor clinical stage, pathologic TNM, and lymphatic invasion (p < 0.05)." (PMID 33833992, 2021).
FAM222A also shares sentences with these, for which no sentence is quoted: Alzheimer disease (2 papers); mild cognitive impairment (1); non-small cell lung carcinoma (1).